FGFR4 (fibroblast growth factor receptor 4)
Description:
Tyrosine-protein kinase that acts as a cell-surface receptor for fibroblast growth factors and plays a role in the regulation of cell proliferation, differentiation and migration, and in regulation of lipid metabolism, bile acid biosynthesis, glucose uptake, vitamin D metabolism and phosphate homeostasis. Required for normal down-regulation of the expression of CYP7A1, the rate-limiting enzyme in bile acid synthesis, in response to FGF19. Phosphorylates PLCG1 and FRS2. Ligand binding leads to the activation of several signaling cascades. Activation of PLCG1 leads to the production of the cellular signaling molecules diacylglycerol and inositol 1,4,5-trisphosphate. Phosphorylation of FRS2 triggers recruitment of GRB2, GAB1, PIK3R1 and SOS1, and mediates activation of RAS, MAPK1/ERK2, MAPK3/ERK1 and the MAP kinase signaling pathway, as well as of the AKT1 signaling pathway. Promotes SRC-dependent phosphorylation of the matrix protease MMP14 and its lysosomal degradation. FGFR4 signaling is down-regulated by receptor internalization and degradation; MMP14 promotes internalization and degradation of FGFR4. Mutations that lead to constitutive kinase activation or impair normal FGFR4 inactivation lead to aberrant signaling.
Synonyms: CD334; JTK2; TKF
Tractability: Small molecule: an approved drug acts on it; a structure with a bound ligand is known; a high-quality ligand is known; it belongs to a druggable protein family. Antibody: its Gene Ontology location is reachable by antibodies, with high confidence; UniProt places it where antibodies can reach, with medium confidence; UniProt predicts a signal peptide or a membrane-spanning region. PROTAC: UniProt records ubiquitination sites on it; ubiquitination databases record sites on it; a small molecule that binds it is known. Other modalities: a drug acting on it is in phase 2 or 3 trials.
Target class: Enzyme; Tyrosine protein kinase FGFR family; Protein Kinase; Kinase; TK protein kinase group
Chemical probes: BLU-9931 (high quality), FGFR4-IN-8B (high quality), FIIN-1 (high quality), FIIN-2 (high quality), FIIN-3 (high quality), INFIGRATINIB (high quality), PD134451, PD134452, PD134453, PD134454, PD134455, roblitinib (high quality)
Gene: Protein-coding gene on chromosome 5 (177,086,456 to 177,098,151, forward strand). Ensembl gene ENSG00000160867.
Subcellular location: Cell membrane; Endosome; Endoplasmic reticulum; Secreted (Isoform 2)
Pathways (Reactome):
Signal Transduction: FGFR4 ligand binding and activation; FRS-mediated FGFR4 signaling; Negative regulation of FGFR4 signaling; PI-3K cascade:FGFR4; PI3K Cascade; PI5P, PP2A and IER3 Regulate PI3K/AKT Signaling; PIP3 activates AKT signaling; Phospholipase C-mediated cascade; FGFR4; RAF/MAP kinase cascade; SHC-mediated cascade:FGFR4; betaKlotho-mediated ligand binding
Disease: Constitutive Signaling by Aberrant PI3K in Cancer; FGFR4 mutant receptor activation; Signaling by FGFR4 in disease
Gene Ontology:
Molecular function: fibroblast growth factor binding; fibroblast growth factor receptor activity; heparin binding; protein binding; protein tyrosine kinase activity; ATP binding; protein kinase activity; transmembrane receptor protein tyrosine kinase activity
Biological process: cell migration; fibroblast growth factor receptor signaling pathway; peptidyl-tyrosine phosphorylation; positive regulation of catalytic activity; positive regulation of cell population proliferation; positive regulation of DNA biosynthetic process; positive regulation of ERK1 and ERK2 cascade; positive regulation of gene expression; positive regulation of proteolysis; protein autophosphorylation; regulation of bile acid biosynthetic process; regulation of extracellular matrix disassembly; response to bile acid; cholesterol homeostasis; glucose homeostasis; phosphate ion homeostasis; regulation of lipid metabolic process; positive regulation of MAPK cascade; regulation of gene expression
Cellular component: cell-cell junction; endoplasmic reticulum; Golgi apparatus; plasma membrane; transport vesicle; receptor complex; endosome; extracellular region; membrane
Genetic constraint (gnomAD): Loss-of-function variants: 63 observed, 87.86 expected, observed/expected ratio (o/e) 0.72, 90% interval 0.58 to 0.88. The upper end of that interval is the gene's LOEUF score, 0.88, which puts it in group 3 of 6, group 1 being the genes least tolerant of losing a copy. Missense variants: 923 observed, 1,096.3 expected, observed/expected ratio (o/e) 0.84, 90% interval 0.8 to 0.89. Synonymous variants: 485 observed, 477.91 expected, observed/expected ratio (o/e) 1.01, 90% interval 0.94 to 1.09.
Cancer hallmarks: proliferative signalling (promotes); invasion and metastasis (promotes)
Homologues: Orthologues: macaque ZNF346 (98% identical), chimpanzee FGFR4 (97% identical), rabbit FGFR4 (94% identical), pig FGFR4 (93% identical), guinea pig FGFR4 (93% identical), dog FGFR4 (91% identical), mouse Fgfr4 (90% identical), rat Fgfr4 (89% identical). Paralogues in human: FGFR3 (60% identical), FGFR2 (58% identical), FGFR1 (56% identical), KDR (29% identical), FLT1 (29% identical), FLT4 (29% identical), PDGFRB (26% identical), CSF1R (26% identical), KIT (26% identical), TIE1 (26% identical), PDGFRA (25% identical), TEK (23% identical), and 41 more.
Diseases named in the same sentence as FGFR4 in open-access papers:
FGFR4 is named in the same sentence as 244 diseases in open-access papers, as found by Europe PMC text mining. Sharing a sentence is not in itself a finding about the gene and the disease. The quoted sentences say what the papers report.
breast cancer (111 papers, 2002 to 2026). A primary or metastatic malignant neoplasm involving the breast. "CRISPR-Cas9 screening from the DepMap database showed that FGFR4 knockout significantly inhibited cell growth or caused cell death in various breast cancer cell lines." (PMID 40091020, 2025). "On the other hand, in breast cancer patients, the minor alleles of rs1966265 and rs351855 in FGFR4 were shown to be strongly associated with breast cancer, and the variant in turn was associated with lymph-node positivity." (PMID 38540215, 2024). "Here, we found that FGFR4 is expressed highly in breast cancer and is associated with poorer outcome." (PMID 39658878, 2024). "The rs1966265 (FGFR4) variant was linked to drug response specifically in cyclophosphamide-epirubicin-docetaxel-based therapy in breast cancer patients, where it was identified as a potential marker for predicting treatment response." (PMID 39592679, 2024). "In TGFα-driven breast cancer incidence, reduced serum Ahsg contributed to a delay in breast cancer progression in FGFR4-deficient mice by altering metabolic pathways such as adipogenesis." (PMID 39684629, 2024). "It is also mentioned that FGFR4 is a target for patients with breast cancer due to the co-expression of FGFR4 and FGF19, associating it with the expression of phosphorylated AKT." (PMID 38540215, 2024). "Mutations in the FGFR4 gene (5q35.2) lead to modifications at K535 and E550 in the kinase domain of the FGFR4 protein in breast cancer patients, causing protein autophosphorylation and activation." (PMID 37296801, 2023). "Few data are available on the association of the FGFR4 gene or FGFR4 protein with specific breast cancer subtypes." (PMID 35193394, 2022). "The FGFR4 gene is located on the chromosomal region 5q35.2, and the FGFR4 protein has been found mutated at K535 and E550 in the kinase domain in breast cancer patients, which causes protein autophosphorylation and activation." (PMID 35193394, 2022). "The FGFR4 Arg388 allele exists in 51% of breast cancer patients and is related to worse progression-free survival." (PMID 35562334, 2022). "Further univariate and multivariate Cox regression analyses revealed that FGFR4 expression was an independent risk factor for HER2-positive breast cancer patients." (PMID 35562334, 2022). "In summary, our study showed that FGFR4 G388R polymorphism is associated with an elevated risk of cancer, especially for prostate and breast cancer." (PMID 33446698, 2021). "A germline FGFR4 mutation identified in breast cancer cell lines, SNP Glycine (G) 388 to Arginine (R) (G388R), was associated with increased FGFR4 expression." (PMID 34068954, 2021). "In this regard, several previous studies have reported an association between FGFR4 and progression of luminal breast cancers." (PMID 34344433, 2021). "Interrogation of public datasets revealed FGFR2 amplification, fusion or mutation in TNBC and other breast cancer subtypes, while FGFR4 overexpression and amplification occurred in all breast cancer subtypes and were associated with poor prognosis." (PMID 34344433, 2021). "FGFR4 rs351855 polymorphism induced higher expression of FGFR4 protein and worse prognosis in breast cancer." (PMID 33017009, 2020). "This FGFR4-associated SNP is important for breast cancer susceptibility, as it causes a receptor conformational change that allows functional interaction with the signal transducer and activator of transcription 3 (STAT3)." (PMID 33081025, 2020). "FGFR4 rs1966265 changes chemotherapy response in breast cancer, higher risk of oral squamous cell carcinoma susceptibility, initiation of cervical cancer (Taiwanese women), and higher risk of breast cancer in Chinese women of Heilongjiang province." (PMID 33017009, 2020). "In this context, it should be noted that a retrospective study has assessed high FGFR4 levels independently associated with the therapeutic response and the survival of ER+ breast cancer patients treated with tamoxifen." (PMID 33081025, 2020).
breast cancer (continued). "FGFR4 rs351855 was repeatedly reported to be associated not only with a higher risk of breast cancer, but also with its aggressiveness and resistance to anti-ER treatment." (PMID 31142340, 2019). "Factor 12 also predicts insensitivity to TOP1-poisons and includes the canonical oncogenes such as ERBB2, TGFB3, ESR1 (AR), and FGFR4 that are strongly associated with breast cancer." (PMID 31695042, 2019). "FGF19 is one of its another nearby gene, and FGF19 and its receptor FGFR4 were strongly associated with the basal-like subtype of breast cancer." (PMID 31921621, 2019). "The FGFRs harbour genetic aberrations such as amplifications of FGFR1, FGFR2 and FGFR4 and mutations in FGFR2 and FGFR4 genes in breast cancer." (PMID 29455658, 2018). "FGFR4 gene rs351855 G>A polymorphism has been associated with genetic predisposition to several types of cancer, including breast cancer, prostate cancer, head and neck cancer, lung cancer, and hepatocellular carcinoma." (PMID 28445975, 2017). "The FGFR4 rs351855 G>A polymorphism was most often studied in breast cancer (6 studies) and prostate cancer (6 studies)." (PMID 28445975, 2017). "Overexpression of FGFR4 has been associated with resistance to chemotherapy in patients with breast cancer." (PMID 29221201, 2017). "High levels of FGFR3 protein expression as well as FGFR4 mRNA expression were associated with poor prognosis of ER+ breast cancer patients receiving TAM treatment." (PMID 27533459, 2016). "The minor alleles of rs1966265 and rs351855 in FGFR4 were strongly associated with breast cancer in the population, with odds ratios of 1.335 (95%CI = 1.154-1.545) and 1.364 (95%CI = 1.177-1.580), respectively." (PMID 26431494, 2015). "Mutations in FGFR4 have been reported in lung cancer and breast cancer, and FGFR4 polymorphisms have been observed in squamous cell carcinoma and breast cancer." (PMID 25894690, 2015). "SNPs rs1966265 and rs351855 in FGFR4 were associated with breast cancer in a northern Chinese population." (PMID 26431494, 2015). "We carried out a case-control study to investigate associations of variants in FGFR3 and FGFR4 with breast cancer in women from Heilongjiang Province." (PMID 26431494, 2015). "In conclusion, we evaluated the associations of four SNPs in the FGFR3 and FGFR4 genes with breast cancer in Chinese women from northeastern China and confirmed the associations of SNPs rs1966265 and rs351855 with breast cancer." (PMID 26431494, 2015). "The results showed that the minor allele of rs1966265 and rs351855 in the FGFR4 gene were strongly associated with breast cancer in Chinese women of Heilongjiang Province, with ORs of 1.335 (95%CI = 1.154-1.545) and 1.364 (95%CI = 1.177-1.580), respectively." (PMID 26431494, 2015). "In this report, we evaluated the local and systemic metabolic effects resulting from a germline deficiency of metabolic regulator FGFR4 on breast cancer development in the MMTV-TGFα mouse model." (PMID 24279986, 2013). "Overexpression of FGFR4 was associated with worse outcome of breast cancer patients." (PMID 39658878, 2024). "In human epidermal growth factor receptor 2 (HER2)+ breast cancer, epigenetic alteration of m6A hypomethylation causes FGFR4 to phosphorylate GSK3β and then activate the β‐catenin/transcription factor 4 signaling pathway, leading to anti‐HER2 therapeutics in tumor cells." (PMID 37750089, 2023). "FGFR4 inhibition enhances susceptibility to anti-HER2 therapy in resistant breast cancer." (PMID 35562334, 2022). "Consistent with our genomic comparison between primary and metastasis, the ESR1 mutation is found by the mean SHAP value as the most predictive feature of metastatic breast cancer, followed by FGFR4 mutation, SOX2 amplification, ERBB2 mutation, and FGFR1 mutation." (PMID 34795255, 2021).
breast cancer (continued). "An SNP in the FGFR4 transmembrane region (rs351855), which involves the substitution of a glycine (G) into an arginine (R), has been associated with a poor prognosis in solid tumors, including breast cancer." (PMID 33081025, 2020). "In addition, supporting this conclusion, FGFR4 overexpression was associated with poor HER2+ breast cancer patient survival." (PMID 30903103, 2019). "Taken together, our results presented here suggested that FGFR4 rs1966265 polymorphisms could be employed as a biomarker for the prediction of clinical outcomes of CET-based chemotherapy in breast cancer patients." (PMID 30359238, 2018). "Moreover, our results indicate that the FGFR4 rs351855 G>A polymorphism increases the risk of prostate and breast cancer, but decreases the risk of lung cancer." (PMID 28445975, 2017). "Since FGFR family proteins have been reported to play a functional role in various cancer types, and the functional role of FGFR4 in basal-like breast cancers remains elusive, we decided to focus on understanding the mechanism underlying FGFR4-mediated cell survival in breast cancer cells." (PMID 27192118, 2016). "In breast cancer, wild type FGFR4 has been proposed to be an important tumor suppressor via the regulation of genes controlling invasion like matrix metalloproteinase 1, suggesting loss of wild type FGFR4 would adversely influence disease progression." (PMID 27154171, 2016). "We found that SNPs rs1966265 and rs351855 in the FGFR4 gene could increase breast cancer risk in northern Chinese women, especially for lymph-node-positive breast cancer." (PMID 26431494, 2015). "Indeed, by combining TGFα overexpression in breast epithelial cells and the FGFR4 deficiency outside the breast, we found that ablation of FGFR4 reduced TGFα-driven breast cancer incidence, delayed breast cancer progression and improved host survival." (PMID 24279986, 2013). "Therefore, we speculate that METTL14 reduction causes the upregulation of FGFR4 expression in HER2-positive breast cancer." (PMID 35562334, 2022). "A single nucleotide polymorphism (SNP) at codon 388 of FGFR4 (Gly388Arg), which encodes an amino acid in the transmembrane domain of the FGFR4 gene, was reported to be associated with poor outcome in sarcoma, prostate, lung, colon, and head and neck carcinomas, melanoma, and advanced breast cancer." (PMID 27966451, 2017). "In a study, researchers utilized patient-derived organoids (PDOs) to explore the efficacy of FGFR4-targeted therapy for breast cancer, with a focus on the luminal A subtype." (PMID 41328353, 2026). "These aberrations highlighted well-known breast cancer-associated genes, such as MDM4, ZNF595, FGFR4, HIST1H1B, TPD52, DECR1, GRB7, and JUP55." (PMID 40162205, 2025). "This study revealed the key role and clinical significance of FGFR4 in pan-cancer and breast cancer through multidimensional analysis." (PMID 40091020, 2025). "Inhibition of FGFR4 enhances the sensitivity of drug-resistant breast cancer (BC) cells to anti-HER2 treatment." (PMID 40271153, 2025). "Strikingly, molecular features that define the HER2E subtype in luminal disease are also consistent in HER2-positive disease, including an epigenetic mechanism for high FGFR4 expression in breast cancer." (PMID 40044693, 2025). "In summary, this study highlighted the critical importance of FGFR4 in both pan-cancer and breast cancer." (PMID 40091020, 2025). "Targeting FGFR4 either by inhibiting it with an antagonistic antibody or silencing it with siRNA enhances the efficacy of doxorubicin in FGFR4-expressing breast cancer lines." (PMID 39796710, 2024). "All these results demonstrated that FGFR4 was closely correlated with fatty acid metabolism in breast cancer." (PMID 39658878, 2024). "Inhibition of FGFR4 restored the chemosensitivity of ADR‐resistant breast cancer cells and reduced the glycolytic flux." (PMID 39658878, 2024).